SERTAD4-AS1 (SERTAD4 antisense RNA 1)
Synonyms: formerly C1orf133
Gene: Long non-coding RNA gene on chromosome 1 (210,231,448 to 210,234,208, reverse strand). Ensembl gene ENSG00000203706.
Diseases named in the same sentence as SERTAD4-AS1 in open-access papers:
SERTAD4-AS1 is named in the same sentence as 1 disease in open-access papers, as found by Europe PMC text mining. Sharing a sentence is not in itself a finding about the gene and the disease.
SERTAD4-AS1 shares sentences with these, for which no sentence is quoted: breast carcinoma (1 paper).